PRAC2 (PRAC2 small nuclear protein)
Synonyms: C17orf93; HOXB-AS5; HOXB13-AS1; NCRNA00253; HOXBAS5
Tractability: No criterion of Open Targets' tractability assessment is met for any kind of drug.
Gene: Protein-coding gene on chromosome 17 (48,722,666 to 48,724,767, forward strand). Ensembl gene ENSG00000229637.
Subcellular location: Nucleus
Gene Ontology:
Cellular component: nucleus
Genetic constraint (gnomAD): Loss-of-function variants: 1 observed, 1.21 expected, observed/expected ratio (o/e) 0.82, 90% interval 0.24 to 1.87. That is too few expected variants to judge how well the gene tolerates losing a copy. Missense variants: 92 observed, 106.06 expected, observed/expected ratio (o/e) 0.87, 90% interval 0.73 to 1.03. Synonymous variants: 43 observed, 44.02 expected, observed/expected ratio (o/e) 0.98, 90% interval 0.76 to 1.26.
Homologues: Orthologues: chimpanzee PRAC2 (98% identical).
Diseases named in the same sentence as PRAC2 in open-access papers:
PRAC2 is named in the same sentence as 10 diseases in open-access papers, as found by Europe PMC text mining. Sharing a sentence is not in itself a finding about the gene and the disease. The quoted sentences say what the papers report.
breast carcinoma (7 papers, 2017 to 2023). "Three of these, TDRD10, PRAC2 and TMEM132C, contained CpG sites that showed diagnostic and prognostic value in breast cancer, particularly in estrogen-receptor (ER)-positive samples." (PMID 30866861, 2019). "Expression of TMEM132C was downregulated across all 13 non-breast cancer cohorts while PRAC2 was upregulated in 77% of cohorts." (PMID 30866861, 2019). "Novel DNA methylation markers were identified, of which cg12374721 (PRAC2), cg18081940 (TDRD10) and cg04475027 (TMEM132C) show promise as diagnostic and prognostic markers in breast cancer as well as other cancer types." (PMID 30866861, 2019). "Using a genome wide approach to analyze the DNA methylation and expression patterns in breast cancer and normal breast, PRAC2, TDR10, and TMEM132C genes have been identified that can serve as novel DNA methylation-gene markers of diagnostic and prognostic significance in breast cancer." (PMID 36185256, 2022). "Sites cg12374721 (PRAC2), cg18081940 (TDRD10) and cg04475027 (TMEM132C) may be effective as diagnostic and prognostic tools not only in breast cancer but also in other cancer types." (PMID 30866861, 2019). "Genes PRAC2, TDR10 and TMEM132C showed differential methylation and differential expression in breast tumor samples relative to normal breast tissue and also contained CpG sites showing diagnostic and prognostic value in breast cancer." (PMID 30866861, 2019). "In addition to the identification of PRAC2, TDR10 and TMEM132C as novel DNA methylation-gene markers in breast cancer, analysis of their expression and diagnostic and prognostic potential revealed they may also be relevant in other cancer types." (PMID 30866861, 2019). "MAGEA1/3/12/13, MMP11/13, PRAC2, CSAG1, COL10/11A1 genes are overexpressed in breast cancer samples from patients with PP." (PMID 36675137, 2023). "Furthermore, 3 CpGs located in genes not previously associated with cancer, PRAC2, TDRD10 and TMEM132C, were able to predict breast cancer overall survival, and more particularly survival of ER-positive patients, suggesting their potential as diagnostic and prognostic markers in BC." (PMID 30866861, 2019).
prostate carcinoma (6 papers, 2005 to 2025). A carcinoma that arises from epithelial cells of the prostate gland. "For this reason PRAC2 was given the name “Prostate Cancer Susceptibility Candidate 2” gene." (PMID 30866861, 2019). "The strongest association we observed was for C17orf93 also known as PRAC2 or HOXB13-AS1, which is highly expressed in prostate, rectum, colon and is a potential prostate cancer susceptibility gene." (PMID 39825380, 2025). "Instead, it is previously identified as prostate cancer susceptibility genes PRAC1 and PRAC2, specifically over-expressed in human prostate and colon cancer." (PMID 34941772, 2021). "Interestingly HOXB13 is located at chromosome band 17q21 immediately adjacent to the PRAC and PRAC2 genes, which have also been proposed as markers of human prostate cancer." (PMID 15583692, 2005). "This may suggest an oncogenic role for PRAC2 in BC, as has been suggested in prostate cancer." (PMID 30866861, 2019).
breast tumor (1 paper, 2019). "Site cg12374721 (PRAC2 gene) was hypermethylated in breast tumor tissue and positively correlated with gene expression (p = 0.0134)." (PMID 30866861, 2019). "PRAC2 is upregulated in breast tumor tissue whereas TDR10 and TMEM132C are both downregulated." (PMID 30866861, 2019). "Thus methylation of this site in breast tumor tissue may contribute to PRAC2 transcriptional activation by blocking the binding of transcriptional repressors." (PMID 30866861, 2019). "In the TCGA dataset, PRAC2 was highly expressed in breast tumor tissue relative to normal tissue." (PMID 30866861, 2019). "Unlike PRAC2, genes TDRD10 and TMEM132C are both downregulated in breast tumor tissue when compared to normal tissue." (PMID 30866861, 2019).
prostate tumors (1 paper, 2026). "Our method also picked up a methylation site in the PRAC2 locus (cg23960088), a region noted as a pan-cancer methylation biomarker in gastrointestinal and prostate tumors, indicating that the integrative approach can recover known epigenetic aberrations." (PMID 41363728, 2026).
thyroid cancer (1 paper, 2023). "We found five TAD blocks with CoMut genes/events specific to ATC with certain mutation frequency in The Cancer Genome Atlas Thyroid Cancer (TCGA-THCA) cohort, including CoMut pairs MAST/NSUN4, AM129B/TRUB2, COL5A1/PPP1R26, PPP1R26/GPSM1/CCDC183, and PRAC2/DLX4." (PMID 36609218, 2023).
cancer (6 papers, 2019 to 2026). A tumor composed of atypical neoplastic, often pleomorphic cells that invade other tissues. "There are plenty of other potential non-coding genes that are likely cancer antigens, including HMHB1, DCANP1 and PRAC2." (PMID 39713347, 2024). "Thus PRAC2, TDR10 and TMEM132C may be more relevant in rapidly growing cancers." (PMID 30866861, 2019).
tumor (3 papers, 2019 to 2021). "Conversely, site cg12374721 (PRAC2) was hypermethylated and positively correlated with gene transcription in tumor tissue." (PMID 30866861, 2019). "Also, the observed upregulation of its adjacent genes (genomic co-ordinates), HOXB13 and PRAC2 allude to possible co-regulatory mechanisms in RSCC, emphasizing their differential roles in proliferation and tumor growth potential within the two tumor types." (PMID 32293332, 2020).
PRAC2 also shares sentences with these, for which no sentence is quoted: colon cancer (1 paper); liver cirrhosis (1); male infertility (1).